IL22 (interleukin 22)
Diseases named in the same sentence as IL22 in open-access papers (continued):
Sharing a sentence is not in itself a finding about the gene and the disease.
uveitis (continued). "Additionally, we investigated the anti-inflammatory effects of cysteamine in a murine model of EAU to determine whether cysteamine has a therapeutic potential effect on patients with uveitis by down-regulating IL-22 and its receptor." (PMID 27166675, 2016). "When comparing uveitis entities, the B27+ AAU group showed significantly increased levels of IL-2, IL-6, IL-18, IL-22, IL-1β, and interferon (IFN)-γ." (PMID 34783307, 2021). "They found higher levels of IL-1β, IL-4, IL-17A, IL-17F, IL-21, IL-22, IL-31, IFN-γ, sCD40L, and TNF-α, with a significant difference for IL-17F, in BD-recurrent uveitis patients respect to the BD-remitted uveitis group, before drug infusion." (PMID 31134098, 2019). "Experimental animal models of uveitis induced by interphotoreceptor retinoid binding protein 1–20 (IRBP1-20) exhibited elevation of hyperplasia RPE and IL-22 production." (PMID 27166675, 2016). "When CD4+ T cells from the uveitis patients were stimulated with IRBP1-20, the production of IL-22 definitely increased." (PMID 27166675, 2016). "The present study showed that IL-22 production by activated PBMCs and CD4+T cells was markedly increased in BD patients with active uveitis as compared to controls." (PMID 23527071, 2013). "Furthermore, up-regulated levels of IL-22 which may compromise the blood-retina barrier and allow biologically active substances and water to enter the retina were found in peripheral blood in uveitis." (PMID 22839430, 2012). "Similar to the result of percent detectable, the vitreous levels of IFN-γ and sCD40L were significantly higher in uveitis group than in PDR group, whereas those of IL-4, IL-17A, IL-22, IL-31, and TNFα were significantly higher in PDR group compared with uveitis group." (PMID 26352837, 2015). "In another study, it was found that IL-22 levels in the supernatants of stimulated PBMCs were higher for BD patients with active uveitis than for patients without uveitis or normal controls." (PMID 25061613, 2014). "An earlier gene expression profiling study by the group of Nussenblatt showed that IL-22 was the gene that showed the highest differential upregulated mRNA expression in noninfectious uveitis patients." (PMID 23527071, 2013). "Of the 40 uveitis patients tested in this study, 15 had no detectable IL-22 mRNA expression, which is consistent with our data showing undetectable IL-22 protein expression by unstimulated PBMCs." (PMID 23527071, 2013). "Significantly higher IL-22 expression was seen in supernatants of activated PBMCs from BD patients with active uveitis compared with BD patients without active uveitis, AAU patients and normal controls." (PMID 23527071, 2013). "However, there are no studies on the biological features of IL-22 in the pathogenesis of uveitis and much remains to be explored about the role of IL-22 in EAU." (PMID 27166675, 2016). "Recent studies have reported the increased number of IL-22 producing T cells in patients with autoimmune noninfectious uveitis; however, the correlation between IL-22 and uveitis remains unclear." (PMID 27166675, 2016). "However, only a part of the IL-22-positive CD4+T cells was also positive for IL-17 in BD patients with active uveitis or without active uveitis and normal controls (31%–41%)." (PMID 23527071, 2013). "Furthermore, the frequency of IL-22 positive CD4+ T cells from BD patients with active uveitis (2.8%±1.14%) was significantly higher than from BD patients without active uveitis (0.97%±0.44%, p = 0.002) or normal controls (1.23%±0.51%, p = 0.005)." (PMID 23527071, 2013). "BD patients with active uveitis showed a significantly higher expression of IL-22 in the supernatants of stimulated PBMCs and CD4+T cells compared with BD patients without active uveitis and normal controls." (PMID 23527071, 2013).
fibrosis (21 papers, 2016 to 2025). the formation of excess fibrous connective tissue in an organ or tissue in a reparative or reactive process. "Therefore, it is understandable how FRB supplementation, which resulted in decreasing the level of Tnf-α and maintaining the levels of Il-10 and Il-22, might have prevented collagen deposition and lowered the risk of fibrosis." (PMID 34070845, 2021). "Studies have reported that an increase in IL-22-positive cells in the liver of HCV-infected patients correlated with fibrosis staging scores and clinical progression from chronic hepatitis to cirrhosis." (PMID 39995661, 2025). "It has also been found that IL-22 binding protein (IL-22BP), an inhibitor of IL-22, can aggravate fibrosis and cirrhosis in chronic HCV-infected patients." (PMID 39995661, 2025). "Plasma IL-10/IL-17A ratio and IL-10/IL-22 ratio significantly differed between F0 fibrosis vs. moderate (F2)." (PMID 40918132, 2025). "In this review, we focus on type 3 immunity and its effector cytokines, IL-17A and IL-22, and their roles in MASLD and MASH-associated fibrosis." (PMID 39156888, 2024). "Using animal models of CVB3-induced chronic myocarditis and DCM, studies have revealed that Th22/IL-22 also has a protective role in chronic viral myocarditis and that IL-22 can inhibit cardiac fibrosis." (PMID 36839448, 2023). "Analysis of IL-17A and associated cytokine expression by immune cells extracted from human liver and stimulated in vitro by mitogens for one week, previously, showed a direct correlation of IL-17A and IL-22 secretion with fibrosis stage." (PMID 36077175, 2022). "IL-17 gene knockout mice with AE-IPF had quicker body weight recovery, milder pulmonary inflammation and fibrosis, stronger IL-22+CD4+T, TGF-β+ γδ T and Treg cell responses, and weaker neutrophil and eosinophil responses than wild-type mice with AE-IPF." (PMID 35836804, 2022). "T lymphocytes play a key role in modulating HSCs activation and hepatic fibrosis by secreting immunomodulatory factors such as IL-17 and IL-22." (PMID 34234100, 2021). "There was no impact of liver steatosis on IL-4, IL-5, IL-10 and IL-22 levels in patients with mild fibrosis." (PMID 39200991, 2024). "On the other hand, other studies reported a negative association between intrahepatic IL-22 levels and liver inflammation as well as fibrosis in CHB patients, probably due to the capacity of IL-22 to promote the survival of hepatocytes and induce the proliferation of LPCs." (PMID 39156888, 2024). "In this report, we found that mTOR inhibitor rapamycin or mTOR deletion in CX3Cr1+ mononuclear phagocytes inhibits expression of interleukin (IL) −23, accompanied by reduced intestinal production of IL-22 and ameliorated fibrosis in the TNBS-induced fibrosis mouse model." (PMID 30765845, 2019). "During CHC treatment, patients with SLD had distinct cytokine and growth factor kinetics, with SLD being the main source of variation in several cytokines (IL-5, IL-9, IL-10, IL-13, IL-17A, IL-22) and growth factors (EGF, VEGF and ANG), and it seems this was independent of fibrosis stage." (PMID 39200991, 2024). "Thus, the lack of IL‐22 signaling appeared to augment the TGF‐β pathway and exacerbate fibrosis in the BLM‐induced fibrosis model." (PMID 34459137, 2021).
polycystic ovary syndrome (21 papers, 2020 to 2025). A disorder that manifests as multiple cysts on the ovaries. "IL-22 can also drive polycystic ovary syndrome (PCOS) associated with ovarian and metabolic dysfunctions." (PMID 36091010, 2022). "Oral contraceptives increased serum IL-22 levels and the IL-22/IL-22BP ratio in females with polycystic ovary syndrome compared to healthy controls." (PMID 39156888, 2024). "The highest-ranked co-cited reference is the article titled “Gut microbiota-bile acid-interleukin-22 axis orchestrates polycystic ovary syndrome” by Qi XY, published in Nature Medicine in 2019." (PMID 39845049, 2024). "It was found that gut-derived interleukin-22 improved the disease phenotype in polycystic ovarian syndrome patients." (PMID 39113805, 2024). "After giving the PCOS-like mice GDCA or interleukin (IL)-22 treatment, hormone abnormalities, estrous cycle disorders, polycystic ovaries, decreased fertility, and insulin resistance were significantly improved." (PMID 34041041, 2021). "Additionally, Escherichia coli Nissle 1917 was found to inhibit mitophagy and ameliorate mitochondrial damage by promoting IL-22 expression in polycystic ovary syndrome mice." (PMID 40004017, 2025). "Gut microbiota–bile acid–interleukin-22 axis orchestrates polycystic ovary syndrome." (PMID 36578840, 2022). "In animal experiments, mice treated with gavage of Bacteroides vulgatus or fecal transplants from PCOS patients showed disruption of the motility cycle and polycystic ovary-like changes, accompanied by IR, altered BAs metabolism, reduced IL-22 secretion and infertility." (PMID 36313343, 2022). "In addition, IL‐22 plays a critical role in bile acid‐mediated regulation of the gut microbiota in individuals with polycystic ovary syndrome." (PMID 33665894, 2021). "Existing research has confirmed that glycodeoxycholic acid induces the secretion of interleukin-22 (IL-22) by group 3 innate lymphoid cells in the intestine, and IL-22 subsequently improves polycystic ovary syndrome (PCOS)." (PMID 38399733, 2024). "Moreover, IL-22 from ILC3s improves the Polycystic ovary syndrome (PCOS) phenotype." (PMID 35574038, 2022). "We found that the administration of IL-22 to DHEA-treated Fshrcre−Stat3f/f mice significantly alleviated irregular estrous cycle, polycystic ovaries and increased corpus luteum numbers." (PMID 38734641, 2024). "Triamterene is an inhibitor of the TGR5 receptor that has been used in a variety of experiments investigating MDMA-induced hyperthermia, Roux-en-Y gastric bypass (RYGB), lung adenocarcinoma, and polycystic ovary syndrome (PCOS) via the microbiota–bile acid–IL22 axis." (PMID 37895888, 2023). "Lower IL-22 may act as a biomarker of improved metabolic health rather than the direct cause, as seen in T2DM and Polycystic Ovary Syndrome (PCOS) where moderate exercise reduces inflammation and improves insulin sensitivity." (PMID 41585797, 2025).
type 2 diabetes (21 papers, 2012 to 2025). "IL-22 is involved in several chronic inflammatory conditions, such as coronary artery disease and type II diabetes mellitus (T2DM), both of which are highly associated comorbidities in patients with CPG." (PMID 38493053, 2024). "This correlation was further supported by type 2 diabetes studies in mice where the relative abundance of Roseburia intestinalis was associated with higher IL-22 production." (PMID 38005995, 2023). "The population-based design and the combination of cross-sectional and prospective analyses to identify associations of serum IL-22 with cardiometabolic risk factors and risk of type 2 diabetes are strengths of this study." (PMID 28143481, 2017). "Similarly, CXCL10, IL-22, IL-21, and IL-1α were negatively associated with the need for mechanical ventilation and coma duration." (PMID 41219650, 2025). "Anti-ANGPTL3/IL22 fusion protein was expressed, purified and then examined for its protective efficacy and the possible mechanism in the db/db murine model of type 2 diabetes." (PMID 36544775, 2022). "More recently, it has been shown that in type 2 diabetes (T2D) and TB co-morbidity serum IL-22 concentrations are further reduced compared to TB patients without co-morbidities." (PMID 30319650, 2018). "Our data argue against the utility of IL-22 as specific biomarker for prevalent or incident type 2 diabetes in humans, but identify potential determinants of IL-22 levels which merits further research in the context of cardiovascular diseases." (PMID 28143481, 2017). "A second hospital-based study observed higher serum IL-22 concentrations in patients with type 2 diabetes, coronary artery disease or both conditions compared with healthy controls." (PMID 28143481, 2017). "The age and sex-adjusted OR (95% CI) per doubling of IL-22 for incident type 2 diabetes of 1.02 (0.85; 1.23) was almost unchanged after consideration of further confounders." (PMID 28143481, 2017). "Thus, our data argue against the utility of IL-22 as biomarker for prevalent or incident type 2 diabetes in humans, but identify potential determinants of IL-22 levels which merits further research in the context of cardiovascular diseases." (PMID 28143481, 2017). "Thus, the absence of the initially hypothesised inverse association between systemic IL-22 levels and type 2 diabetes in our study may not be attributable to the advanced age of the KORA F4 study population." (PMID 28143481, 2017). "Previous clinical studies found that plasma levels of IL-22 and the number of IL-22-producing CD4+ T cells were higher in insulin-resistant or type 2 diabetic obese individuals than in insulin-sensitive obese or lean individuals, but results were based on very small samples." (PMID 28143481, 2017). "Baseline serum IL-22 levels (median, 25th/75th percentiles) for incident type 2 diabetes cases and non-cases were 6.28 (1.95; 12.35) and 6.45 (1.95; 11.80) pg/ml, respectively (age and sex-adjusted P = 0.744)." (PMID 28143481, 2017). "In our analyses of serum cytokine profiles, no cytokine differed significantly between T2DM patients and controls, except IL-22, whereas levels of these cytokines were increased or undetectable in patients with type 2 diabetes." (PMID 22312190, 2012). "However, serum IL-22 did neither differ between groups with different glucose tolerance status nor between individuals with normal glucose tolerance, prediabetes (IFG and/or IGT) or type 2 diabetes at all levels of adjustment." (PMID 28143481, 2017). "In another study, IL-22 is mainly produced by two subsets of ILCs, lymphoid tissue inducer (LTi) cells (50%) and NCR+ ILC3s (18%), and is significantly reduced in Mtb-infected mice with type 2 diabetes mellitus (T2DM) than in Mtb-infected mice without T2DM." (PMID 33718260, 2021).
allergic asthma (20 papers, 2011 to 2025). A asthma with a basis in a pathological type I hypersensitivity reaction. "Further, a murine model of allergic asthma using OVA immunization in IL-22-deficient mice showed reduced lung inflammation during the sensitization phase but increased lung inflammation during the antigen challenge (inhibited by exogenous IL-22)." (PMID 23300440, 2012). "Next, we evaluated whether the IL-22 deficiency would affect allergic asthma that courses with neutrophil inflammation." (PMID 37445595, 2023). "Unlike allergic asthma associated with eosinophilia and Th2 cytokines, non-allergic asthma is often marked by neutrophil-dominated inflammation and the involvement of other T helper cell subsets, such as Th1 and Th17, which produce cytokines like IL-17, IL-21, and IL-22." (PMID 39664985, 2024). "Our study shows an original finding when we described that the pro-inflammatory function of IL-22 was dependent on simultaneous secretion of IL-17 by Th17 cells in allergic asthma." (PMID 37445595, 2023). "Because we showed a pro-inflammatory function for IL-22 in allergic asthma, we evaluated the frequency and number of CD11c+CD11b+ DC ex vivo, which were negatively regulated in IL-22 KO mice exposed to the allergen compared to WT OVA group." (PMID 37445595, 2023). "In summary, our data suggest that IL-22 acts as a pro-inflammatory cytokine in allergic asthma, contributing to the survival of eosinophils and increase in CD11b+ DC in the lungs." (PMID 37445595, 2023). "Our results show that targeting IL-22 would negatively affect the survival of eosinophils, reduce the expansion or migration of CD11c+CD11b+ cells, and negatively regulate allergic asthma." (PMID 37445595, 2023). "IL-22 level in nasal lavage negatively correlated with eosinophil count in nasal smear in patients with allergic rhinitis and allergic asthma (rs = − 0.83, p < 0.05)." (PMID 33478443, 2021). "Our study showed that IL-22 level in nasal lavage negatively correlated with eosinophil count in nasal smear in patients with allergic rhinitis and allergic asthma." (PMID 33478443, 2021). "Despite the evidence that IL-22 can be important in the pathogenesis of allergic asthma and allergic rhinitis scientists argue if this cytokine acts as proinflammatory or anti-inflammatory agent." (PMID 33478443, 2021). "Consistent with previous findings, the expression level of IL-22 in allergic asthma mice was higher than that in control mice." (PMID 34836520, 2021). "Previous studies have demonstrated that IL-22 level was higher in allergic asthma than in healthy control." (PMID 34836520, 2021). "In A. fumigatus live conidia allergic asthma chronic model, dectin-1 was shown to promote IL-22 and immunopathology, corroborating other findings showing a detrimental role of dectin-1 in fungal-induced allergic asthma." (PMID 29696023, 2018). "For example, administration of recombinant murine IL-22, use of neutralizing IL-22 antibody or IL-22 plasmid DNA during sensitization or challenge phase as well as IL-22 knockout mice were used in allergen induced allergic asthma models." (PMID 25254361, 2014). "Th17 cells as well as the concentrations of IL-17 and IL-22, have also been shown to be increased with the severity of allergic asthma." (PMID 24991220, 2014). "ILCs that secrete IL-22 have been identified recently in the lungs of mice during a model of experimental allergic asthma, and experiments using Il22−/− mice demonstrated that IL-22 plays a protective role in limiting AHR and airway inflammation." (PMID 23562755, 2013). "Further in vivo investigations are required to establish the effect of IL-22 inhibition on the progression of airway remodeling in chronic allergic asthma." (PMID 24283210, 2013). "To define the role of IL-22 in allergic responses within the lung, we applied a model of allergic asthma in mice sensitized to ovalbumin (OVA)." (PMID 21789181, 2011).